FOXD4L5 (forkhead box D4 like 5)
Synonyms: bA15J10.2; OTTHUMG00000013332
Tractability: No criterion of Open Targets' tractability assessment is met for any kind of drug.
Gene: Protein-coding gene on chromosome 9 (65,282,101 to 65,285,209, reverse strand). Ensembl gene ENSG00000204779.
Subcellular location: Nucleus
Subcellular location (Human Protein Atlas): Nucleoplasm
Gene Ontology:
Molecular function: DNA-binding transcription factor activity, RNA polymerase II-specific; RNA polymerase II cis-regulatory region sequence-specific DNA binding; DNA-binding transcription factor activity; sequence-specific DNA binding
Biological process: anatomical structure morphogenesis; cell differentiation; regulation of transcription by RNA polymerase II; regulation of DNA-templated transcription
Cellular component: chromatin; nucleus
Genetic constraint (gnomAD): Loss-of-function variants: 0 observed, 7.31 expected, observed/expected ratio (o/e) 0, 90% interval 0 to 0.41. That is too few expected variants to judge how well the gene tolerates losing a copy. Missense variants: 5 observed, 161.92 expected, observed/expected ratio (o/e) 0.0309, 90% interval 0.015 to 0.065. Synonymous variants: 2 observed, 66.34 expected, observed/expected ratio (o/e) 0.0301, 90% interval 0.011 to 0.095.
Homologues: Orthologues: mouse Foxd4 (50% identical). Paralogues in human: FOXD4L4 (99% identical), FOXD4L6 (98% identical), FOXD4L3 (98% identical), FOXD4 (84% identical), FOXD4L1 (71% identical), FOXD1 (33% identical), FOXD2 (31% identical), FOXD3 (30% identical), FOXE3 (25% identical), FOXC1 (23% identical), FOXE1 (23% identical), FOXC2 (22% identical), and 29 more.
Diseases named in the same sentence as FOXD4L5 in open-access papers:
FOXD4L5 is named in the same sentence as 2 diseases in open-access papers, as found by Europe PMC text mining. Sharing a sentence is not in itself a finding about the gene and the disease.
FOXD4L5 shares sentences with these, for which no sentence is quoted: cancer (1 paper); lung carcinoma (1).